ENSG00000187186 (novel protein)
Synonyms: LOC730098
Gene: Protein-coding gene on chromosome 9 (34,664,163 to 34,666,122, reverse strand). Ensembl gene ENSG00000187186.
Homologues: Orthologues: mouse Gm20878 (84% identical), mouse Gm21586 (84% identical), mouse Gm21953 (84% identical).